PAEP (progestagen associated endometrial protein)
Description:
Glycoprotein that regulates critical steps during fertilization and also has immunomonomodulatory effects. Four glycoforms, namely glycodelin-S, -A, -F and -C have been identified in reproductive tissues that differ in glycosylation and biological activity. Glycodelin-A has contraceptive and immunosuppressive activities. Glycodelin-C stimulates binding of spermatozoa to the zona pellucida. Glycodelin-F inhibits spermatozoa-zona pellucida binding and significantly suppresses progesterone-induced acrosome reaction of spermatozoa. Glycodelin-S in seminal plasma maintains the uncapacitated state of human spermatozoa.
Synonyms: GD; PP14; PAEG; ZIF-1; PEP; GdA; GdS; GdF; MGC138509; MGC142288
Tractability: Antibody: UniProt places it where antibodies can reach, with high confidence; its Gene Ontology location is reachable by antibodies, with high confidence; UniProt predicts a signal peptide or a membrane-spanning region.
Gene: Protein-coding gene on chromosome 9 (135,561,756 to 135,566,955, forward strand). Ensembl gene ENSG00000122133.
Subcellular location: Secreted
Gene Ontology:
Molecular function: protein binding; small molecule binding
Biological process: apoptotic process; negative regulation of sperm capacitation; positive regulation of granulocyte macrophage colony-stimulating factor production; regulation of binding of sperm to zona pellucida
Cellular component: extracellular region
Genetic constraint (gnomAD): Loss-of-function variants: 28 observed, 23.1 expected, observed/expected ratio (o/e) 1.21, 90% interval 0.9 to 1.65. The upper end of that interval is the gene's LOEUF score, 1.65, which puts it in group 6 of 6, group 1 being the genes least tolerant of losing a copy. Missense variants: 209 observed, 212.73 expected, observed/expected ratio (o/e) 0.98, 90% interval 0.88 to 1.1. Synonymous variants: 103 observed, 85.44 expected, observed/expected ratio (o/e) 1.21, 90% interval 1.03 to 1.42.
Homologues: Orthologues: chimpanzee PAEP (84% identical), macaque PAEP (83% identical), pig PAEP (42% identical). Paralogues in human: LCN9 (21% identical), OBP2A (19% identical), OBP2B (18% identical), LCN1 (18% identical), PTGDS (17% identical), LCN10 (16% identical), LCN15 (16% identical), LCN2 (16% identical), LCN8 (15% identical), LCN6 (14% identical), LCN12 (13% identical), LCNL1 (8% identical).
Diseases named in the same sentence as PAEP in open-access papers:
PAEP is named in the same sentence as 52 diseases in open-access papers, as found by Europe PMC text mining. Sharing a sentence is not in itself a finding about the gene and the disease. The quoted sentences say what the papers report.
endometriosis (9 papers, 2015 to 2024). The growth of functional endometrial tissue in anatomic sites outside the uterine body. "Progesterone-associated endometrial protein (PAEP) can be used as a non-invasive biomarker to break down endometriosis." (PMID 35087563, 2021).
melanoma (6 papers, 2015 to 2025). A malignant, usually aggressive tumor composed of atypical, neoplastic melanocytes. "Recently, we reported that the oncogenesis and development of melanoma are closely related to the expression level of the protein, progestagen-associated endometrial protein (PAEP)." (PMID 25785839, 2015). "PAEP (progestagen-associated endometrial protein) is normally produced by the placenta and endometrium and has been reported to suppress T-cell function in melanoma." (PMID 40717170, 2025). "We recently reported a high level of PAEP gene expression in melanoma, with a concomitant increase in the proliferation, migration and invasion of melanoma cells." (PMID 25785839, 2015). "Collectively, the results indicated that the PAEP protein secreted by melanoma cells primarily inhibited the activation of Th1 cells, but not Th2 cells." (PMID 25785839, 2015). "Although PAEP is a well-known lymphocyte regulatory molecule, its true function in the development and metastasis of melanoma in the tumor microenvironment remains unclear." (PMID 25785839, 2015). "This suggests that the melanoma-derived PAEP protein inhibit the proliferation of lymphocytes." (PMID 25785839, 2015). "Our result suggests that melanoma cell-secreted PAEP protein immunosuppresses the activation, proliferation and cytotoxicity of T lymphocytes, which might partially explain the mechanism of immune tolerance induced by melanoma cells within the tumor microenvironment." (PMID 25785839, 2015).
ovarian carcinoma (6 papers, 2012 to 2023). A malignant neoplasm originating from the surface ovarian epithelium. "Higher expression of glycodelin A (PAEP) in ovarian cancer tumours is associated with both a lower overall patient survival and a shorter relapse-free survival time." (PMID 35406529, 2022). "These include genes such as PAEP, which encodes the protein glycodelin, a lipocalin protein associated with reproductive cancers including breast cancer, ISG15, a prognostic marker in breast cancer, and ANKRD1, which has been associated with lung and ovarian cancer." (PMID 34681087, 2021).
colon cancer (2 papers, 2022 to 2025). "Conversely, protective genes such as PAEP, TAP2, CXCL10, and IRF1 were notably down-regulated in colon cancer cells." (PMID 40959081, 2025).
Infertility (2 papers, 2019 to 2023). "PAEP, ESR1, and PGR are indeed normally finely regulated, and their abnormalities in patients with luteal phase defects are associated with infertility." (PMID 31375021, 2019).
adenomyosis (1 paper, 2022). The growth of endometrial tissue inside the muscular wall of the uterine corpus. "Adenomyosis organoids showed higher expression of TGF-β2 and SMAD3 and increased gene expression of SPP1, PAEP, LIF, and 17βHSD2 compared with control organoids." (PMID 35207707, 2022). "SPP1, PAEP, LIF, and 17βHSD2 expression were upregulated in adenomyosis sec- and gest-organoids compared with control organoids, indicating possible molecular mechanisms involved in adenomyosis-impaired implantation and pregnancy disorders." (PMID 35207707, 2022).
allergic reactions (1 paper, 2019). "These loci were localized at the beginning of the coding region of two genes encoding for the proteins CSN2 and PAEP, both present in cow milk and responsible for allergic reactions in humans." (PMID 31624292, 2019).
epilepsy (1 paper, 2025). A brain disorder characterized by episodes of abnormally increased neuronal discharge resulting in transient episodes of sensory or motor neurological dysfunction, or psychic dysfunction. "We analyzed OLINK proteomics data from a large epilepsy cohort in which we have previously found four differentially expressed proteins (CDH15, PAEP, LTBP3, PHOSPHO1)." (PMID 40591616, 2025).
metastatic tumor (1 paper, 2023). "Recent studies showed other proteins such as PAEP, pp12, and pp14 upregulated in metastatic tumor cells to hamper NK cell function." (PMID 37190251, 2023).
Sepsis (1 paper, 2024). Sepsis is defined as life-threatening organ dysfunction caused by a dysregulated host response to infection. "We established a prognostic model consisting of four sepsis-related genes: KRT20, PAEP, CCR3, and ANLN." (PMID 39421149, 2024).
squamous cell carcinoma (1 paper, 2018). A carcinoma arising from squamous epithelial cells. "Here, the expression of PAEP was significantly higher in adenocarcinoma (ADC) compared to squamous cell carcinoma (SQCC)." (PMID 30518088, 2018).
tumor (27 papers, 2009 to 2025). "LRP1, AKT2, PI3, IL27RA, OBP2A, and PAEP were found to be more expressed in OC tumour samples than in normal tissues." (PMID 39063239, 2024). "Gata3 plays a key role in airway remodeling during organ development and this transcription factor functions as a tumor suppressor by controlling the expression of lung metastasis inhibitors (DLC1 (deleted in liver cancer 1) and PAEP (progestagen-associated endometrial protein)." (PMID 26427040, 2015). "Further multivariate analysis unveiled significant insights: LRP1, PAEP, PI3, OBP2A, and IL27RA genes exhibited higher levels in the tumour group, whereas FOS, PDGFRA, and FGF7 showed higher expression in normal ovarian tissue (all p < 0.001)." (PMID 39063239, 2024). "In summary, the data highlight the importance of these IRGs in both promoting and preventing tumour progression by indicating a strong correlation between the expression level of genes such as LRP1, PI3, PAEP, FOS, FGF7, and PDGFRA and the degree of tumour immune infiltration in OC." (PMID 39063239, 2024). "A heatmap of the 110 CpGs shows overall lower methylation of these CpGs in tumors compared to adjacent non-tumor tissues: the top five hypermethylated genes were GLRX, WNT9B, SEPT9, KIAA00284, and PPYR1, and the top five hypomethylated genes were KIAA0748, PAEP, PCDH15, PTPRN2, and DUSP27." (PMID 34635168, 2021).
cancer (11 papers, 2015 to 2025). A tumor composed of atypical neoplastic, often pleomorphic cells that invade other tissues. "The results indicated that seven risk genes (SERPINE1, LAMC2, MYLK, IL21R, KRT81, MAMDC2, and PAEP) of the signature were differentially expressed in the cancer tissues compared to the normal tissues." (PMID 37636564, 2023). "Another lipocalin associated with carcinoma is glycodelin, also called PAEP (progestagen-associated endometrial protein)." (PMID 26131602, 2015). "Actually, studies on the role of GOPC, PAEP and IDE in STAD are mostly lacking, but they all have important roles in other cancer types." (PMID 35859893, 2022).
brain diseases (1 paper, 2025). "While the roles of PAEP, CCN5, and XG in brain diseases are not yet fully understood, our study identifies significant associations between these proteins and brain structure, offering a valuable basis for future studies." (PMID 40456753, 2025).
PAEP also shares sentences with these, for which no sentence is quoted: infection (125 papers); viral infection (26); breast carcinoma (4); latent infection (4); genital herpes (3); endometrial cancer (2); herpes infection (2); influenza (2); neuroblastoma (2); abortion (1); adenocarcinoma (1); Anxiety (1); autoimmune disease (1); avian influenza (1); cardiovascular disorder (1); cervical cancer (1); chickenpox (1); co-infection (1); colorectal cancer (1); depression (1); enteritis (1); gastric cancer (1); glioma (1); hematoma (1); hepatocellular carcinoma (1); HIV-1 infection (1); iron deficiency (1); kidney cancer (1); leukemia (1); lung carcinoma (1).
A further 8 diseases each share a sentence with PAEP in 1 paper.